EGFR (epidermal growth factor receptor)
Diseases named in the same sentence as EGFR in open-access papers (continued):
Sharing a sentence is not in itself a finding about the gene and the disease.
lung adenocarcinoma (continued). "Our study aimed to harness the power of CT scans, observed over time, in predicting how lung adenocarcinoma patients might respond to a treatment known as EGFR-TKI." (PMID 37958300, 2023). "Indeed, advanced EGFR-mutant lung adenocarcinoma patients with higher PD-L1 expression had worse PFS, OS, and a lower frequency of secondary T790M mutation." (PMID 37340370, 2023). "In our study, higher BMI became significantly associated with poorer PFS by multivariate analysis, this may be due to different patient population since our study focused on patients with EGFR-mutant lung adenocarcinoma and relatively small population size." (PMID 37340370, 2023). "We performed this retrospective study to eliminate the impact of potential confounding factors on the results to explore the necessity of craniocerebral radiotherapy for EGFR-mutant lung adenocarcinoma patients with brain metastases used propensity score matching (PSM)." (PMID 36845694, 2023). "The high incidence of epidermal growth factor receptor (EGFR) mutations is usually found in female patients with lung adenocarcinoma who have never-smoked." (PMID 37014455, 2023). "Adjuvant EGFR‐TKIs could significantly improve DFS among patients with stage IB lung adenocarcinoma compared with CO, with a safe and tolerable profile." (PMID 37559419, 2023). "Third, as we focused on and examined EGFR mutation‐positive adenocarcinomas, it will also be necessary to study EGFR mutation‐negative specimens before any conclusion can be generalized to all lung adenocarcinomas." (PMID 37004157, 2023). "EGFR mutant lung adenocarcinomas in a Caucasian population represent <15% of all adenocarcinomas." (PMID 37169023, 2023). "Hence, further studies on the immune microenvironment of EGFR-mutant lung adenocarcinoma were of great significance for improving the efficacy of immunotherapy in EGFR-mutant lung adenocarcinoma patients in the future." (PMID 37035883, 2023). "In East Asia, approximately half of lung adenocarcinoma (ADC) patients have epidermal growth factor receptor (EGFR) mutations, and tyrosine kinase inhibitor (TKI) therapy is the standard treatment for advanced EGFR-mutant lung ADC." (PMID 37340370, 2023). "Our study provides insight into changes in secreted proteins during EGFR driven lung adenocarcinoma transformation that may play a role in the processes that promote tumor progression." (PMID 38260835, 2023). "We developed a set of algorithms to assess EGFR status and morphology using a real-world advanced lung adenocarcinoma cohort of 2099 patients with hematoxylin and eosin (H&E) images exhibiting high morphological diversity and low tumor content relative to public datasets." (PMID 36927889, 2023). "Combining various feature engineering-based radiomic paths could compare their performances and identify paths built with the most appropriate methods to predict EGFR-mutant lung adenocarcinoma in 18FDG PET/CT." (PMID 36810090, 2023). "In addition, DCLK1 expression was markedly increased in EGFR-TKI-resistant lung adenocarcinoma cells." (PMID 37239162, 2023). "In addition, our previous study confirmed that the increased expression of DCLK1 in lung adenocarcinoma contributes to EGFR-TKI-acquired resistance, partly due to the maintenance of tumor cell stemness." (PMID 37239162, 2023). "EGFR gene mutation is the most common and important type of gene mutation in lung adenocarcinoma, we conducted subgroup analysis on 99 EGFR gene mutation nodules." (PMID 37124493, 2023). "Patient#A was a 69-year-old male, former smoker, treated for a lung adenocarcinoma TTF1+ without EGFR, KRAS, or BRAF mutation or ALK or ROS1 translocation but an expression of 100% of PDL1 on the tumor cell." (PMID 37370798, 2023). "EGFR mutant lung adenocarcinoma cell lines H1975 (L858R/T790M), PC9 (Del." (PMID 37190191, 2023).
lung adenocarcinoma (continued). "Thus, this study aimed to explore the potential role of markers, including neutrophil to lymphocyte ratio, platelet to lymphocyte ratio, and Prognostic Nutritional Index in patients with stage I EGFR-altered lung adenocarcinoma." (PMID 37941434, 2023). "We also evaluated the presence of EGFR mutations in this population, as EGFR mutations are common in Asian patients with lung adenocarcinoma, particularly in nonsmoking female patients." (PMID 36653333, 2023). "Epidermal growth factor receptor (EGFR) wild type lung adenocarcinoma, the GAS5 SNP rs145204276, may aid in tumor stage, distal metastases, and lymph node metastasis prediction." (PMID 37888204, 2023). "In this study, the biological function of DCLK1 in EGFR-TKI-resistant lung adenocarcinoma via remodeling the EMT process was explored through in vitro and in vivo experiments, with the aim of finding potential therapeutic targets in EGFR-TKI-resistant lung adenocarcinoma." (PMID 37239162, 2023). "We conclude that LCT may improve clinical outcomes, in terms of PFS and OS, in patients with advanced EGFR-mutant lung adenocarcinomas who are treated with first-line afatinib." (PMID 37046679, 2023). "Four patients with lung adenocarcinoma (LUAD) who carried no EGFR/ALK mutations histologically evolved into SCLC." (PMID 38022621, 2023). "While most bone metastases of NSCLC present as lytic or mixed types, a previous study reported that the presence of sclerotic metastatic lesions was associated with a good prognosis compared to other types of metastases in epidermal growth factor receptor (EGFR)-mutant lung adenocarcinoma." (PMID 37674153, 2023). "Clearly, exploring the resistance mechanism and searching for new therapeutic targets to delay and reverse EGFR-TKIs resistance in lung adenocarcinoma is an urgent problem to be solved in tumor-targeted therapy and it is also essential for the treatment of NSCLC." (PMID 36744262, 2023). "The authors further analyzed the relationship between FKBP10 expression and EGFR mutation status and found that the expression of FKBP10 is similar between lung adenocarcinoma brain metastases bearing EGFR mutations and EGFR non-mutants." (PMID 37201304, 2023). "Thus, we devised and conducted this real‐world study to evaluate the efficacy and safety of adjuvant EGFR‐TKIs for completely resected stage IB lung adenocarcinoma." (PMID 37559419, 2023). "In patients with stage IV EGFR-mutant lung adenocarcinoma, high E-cadherin expression in the lung tumor might be associated with worse OS." (PMID 37340370, 2023). "In patients with stage IV EGFR-mutant lung adenocarcinoma, high E-cadherin expression in the lung tumor might be associated with worse OS, and vimentin expression in the lung tumor was positively related to the risk of brain metastasis." (PMID 37340370, 2023). "Precise quantification of VAF is not mandatory in the context of EGFR mutant lung adenocarcinoma, as these mutations are commonly driver mutations and not subclonal." (PMID 37958668, 2023). "We also identified several proteins that could be potentially useful markers for diagnosis of malignancies and might affect the malignant progression of EGFR‐positive early lung adenocarcinomas." (PMID 37004157, 2023). "Of these, EGFR mutation occurs in 55% of Asian patients and 15% of non-Asian patients with lung adenocarcinoma, followed by ALK rearrangement occurs in 5–8%, and other mutations are limited to 5% of non-squamous NSCLC." (PMID 37789413, 2023). "Overall, 67 lung adenocarcinoma samples were examined: 34 with epidermal growth factor receptor gene (EGFR) mutations and 33 without EGFR mutations." (PMID 37131310, 2023). "Our study showed that EGFR mutations are not a prognostic factor for patients with early-stage lung adenocarcinoma." (PMID 36766495, 2023). "Baseline clinical data of 17 cases of EGFR-mutant lung adenocarcinoma." (PMID 36756152, 2023).
lung adenocarcinoma (continued). "Here, we report a case of pretreated advanced lung adenocarcinoma with EGFR ex20ins (NM_005228: exon 20:c.2316_2321dup: p.773_774dup) benefiting from combined furmonertinib, a novel third-generation EGFR-TKI, with anlotinib, a novel multi-targeting tyrosine kinase inhibitor, for a long time." (PMID 36817153, 2023). "TGF-β-induced factor homeobox 2 (TGIF2) phosphorylation triggered the EGFR–RAS–ERK signaling pathway to enhance the stemness of lung adenocarcinoma cells, thus promoting its progression; by silencing TGIF2, there is a decrease of cancer stem cell-like properties in NSCLC cells." (PMID 37190223, 2023). "To the best of our knowledge, we are the first to report that the combination of furmonertinib and anlotinib is an effective treatment strategy in a patient with EGFR ex20ins-positive advanced lung adenocarcinoma who was previously treated with platinum-based chemotherapy." (PMID 36817153, 2023). "However, it is undeniable that EGFR is a determinant driving lung adenocarcinoma growth and treatment response in vivo." (PMID 37065830, 2023). "EGFR is one of the most common tumor driver gene of lung adenocarcinoma." (PMID 37223682, 2023). "Regardless of the combination of other treatments, EGFR mutation with TKI therapy is recommended as a positive prognostic factor for patients with lung adenocarcinoma." (PMID 37833769, 2023). "In addition, similar results were obtained from the immunofluorescence assay, confirming the involvement of DCLK1 in remodeling the EMT process and influencing the sensitivity of lung adenocarcinoma cells to EGFR-TKI." (PMID 37239162, 2023). "Additionally, in lung adenocarcinoma, loss of DSG2 (via gene silencing) leads to the nuclear translocation of EGFR, as well as suppression of EGFR signaling via the Src-Rac1-PAK1 pathway." (PMID 38188287, 2023). "Interestingly, the frequency of activating EGFR mutations, detected in 3/175 (1.7%) patients is much lower than in other subtypes of NSCLC, e.g., adenocarcinoma of the lung (ACA) with an incidence of 12.7% reported in our previous work." (PMID 37445733, 2023). "We hope to develop a radiomics model combining intratumoral and peritumoral features to predict EGFR mutation status in lung adenocarcinoma patients non-invasively." (PMID 37749461, 2023). "More frequent HCMV, EBV, HPV16, and HPV18 infections were observed in lung adenocarcinoma samples with EGFR mutations than in samples without these mutations." (PMID 37131310, 2023). "Sequencing of the EGFR gene is equally essential in patients with early lung adenocarcinoma." (PMID 37390230, 2023). "However, EGFR has been proven to be a determinant driving lung adenocarcinoma growth and treatment response in vivo, thus subsequent analysis will also be performed for EGFR." (PMID 37065830, 2023). "Although EGFR-TKIs have been demonstrated to be associated with improved ORR and PFS in advanced EGFR-mutant lung adenocarcinoma more than traditional chemotherapy regimens, the development of resistance to EGFR-TKIs typically occurs within 10–14 months after treatment initiation." (PMID 37046679, 2023). "A total of 79 patients were diagnosed as EGFR‐mutant lung adenocarcinoma with bone metastases." (PMID 35614541, 2023). "Here, we aimed to evaluate the prognostic impact of EGFR and KRAS mutations by considering the relationship between these mutations and their histological subtype and/or tumor invasion status in resected pTis-3N0M0 lung adenocarcinoma." (PMID 36918771, 2023). "This study aimed to develop a pipeline for selecting the best feature engineering-based radiomic path to predict epidermal growth factor receptor (EGFR) mutant lung adenocarcinoma in 18F-fluorodeoxyglucose (FDG) positron emission tomography/computed tomography (PET/CT)." (PMID 36810090, 2023).
lung adenocarcinoma (continued). "Since 2004, oncogene addiction has been demonstrated in terms of DNA mutations in the EGFR (exon 19–21); B-RAF (V600E); MET (exon 14 skip mutations); intragenic insertions in EGFR and ERB-B2 (exon 20); or fusion rearrangements in ALK, ROS1, RET, NTRK, and NRG1 in patients with lung adenocarcinoma." (PMID 37628803, 2023). "The ICAPE study confirmed icotinib’s safety and efficacy in treating EGFR mutant lung adenocarcinoma, regardless of the EGFR mutation type." (PMID 37251922, 2023). "In addition, these studies further emphasized that excessive activation of EMT leads to acquired resistance of lung adenocarcinoma cells to EGFR-TKI." (PMID 37239162, 2023). "The present study evaluated the incidence of EGFR mutations among smokers and nonsmokers with lung adenocarcinomas." (PMID 37425232, 2023). "In a multicenter retrospective study, researchers found adjuvant EGFT-TKIs might be a beneficial choice compared with EGFR-TKIs plus chemotherapy in EGFR-mutant stage III-pN2 lung adenocarcinoma." (PMID 36782320, 2023). "Compared with systemic chemotherapy, EGFR-TKI targeted combined chemotherapy for stage-IV lung adenocarcinoma can increase the immune function of patients, more effectively inhibit the growth and proliferation of tumor cells, and reduce the level of oxidative stress." (PMID 37250563, 2023). "Based on our previous study, the main purpose in this retrospective study was to investigate the prognostic value of SII and related inflammatory factors (NLR, PLR and LMR) before thoracic radiotherapy for predicting OS in patients with advanced EGFR mutant lung adenocarcinomas." (PMID 36070068, 2023). "Patient#B was a 53-year-old male, current smoker, with a lung adenocarcinoma TTF1+ PDL1 0% without EGFR, KRAS, or BRAF mutation or ALK and ROS1 translocation but STK11 mutation." (PMID 37370798, 2023). "Thus, we aimed to develop and validate a radiomic model to identify the early acquired resistance to EGFR-TKIs in lung adenocarcinomas before radiographic advance." (PMID 37730961, 2023). "Furthermore, CD109 maintains cancer stem-like properties or promotes tumorigenicity and metastasis by interacting with EGFR in lung adenocarcinoma, cervical squamous cell carcinoma, and HNSCC." (PMID 37373457, 2023). "Several studies have reported a more lepidic pattern of lung adenocarcinoma in patients with EGFR mutations which is not consistent with our study." (PMID 36766495, 2023). "This study found that T790M mutation is more likely to occur in female, non-smoking, non-emphysema lung adenocarcinoma patients, and these clinical features are as same as EGFR mutation, which was reported in the literature." (PMID 37697337, 2023). "CLDN-2 expression is increased via an EGFR/MEK/ERK/c-Fos pathway in lung adenocarcinoma A549 cells." (PMID 36961882, 2023). "Interestingly, one of the resistance mechanisms in EGFR inhibitor treatments is the transdifferentiation of lung adenocarcinoma to small cell neuroendocrine cancer." (PMID 36754910, 2023). "However, this is contradicted by a study showing that CBLC promoted lung adenocarcinoma development through activating EGFR." (PMID 38045004, 2023). "Of the 45 lung adenocarcinoma never-smoker patients with known EGFR status, 33 (73.3%) had EGFR-mutated tumors." (PMID 37461096, 2023). "According to one Korean dataset, there were four patients (1.8%) with a BRAF mutation among 222 Stage III/IV lung adenocarcinoma patients without EGFR/ALK aberrations." (PMID 37374289, 2023). "Although it has been reported that 80% of lung adenocarcinoma with PIK3CA mutations is associated with EGFR mutations, no cases with pathogenic co-mutation of PIK3CA and EGFR were detected in our PPC cohort." (PMID 36243681, 2022). "In lung adenocarcinoma, the median OS was 14 months when treated with pemetrexed-platinum doublet chemotherapy, but the value increased to 39 months upon treatment with a third-generation EGFR tyrosine kinase inhibitor (TKI)." (PMID 36230708, 2022).
lung adenocarcinoma (continued). "In conclusion, our case is of significant importance to clinicians involved in the treatment of patients with advanced non-smoking lung adenocarcinoma and no EGFR mutations." (PMID 35029237, 2022). "Second, among the 703 patients with pathological stage IB-IIIA primary lung adenocarcinoma during the analysis period, 8.3% and 8.5% of the patients did not undergo EGFR mutation analysis and PET-CT, respectively." (PMID 36085020, 2022). "Thus, to date, the value and timing of BRT for patients with BM from lung adenocarcinoma have remained controversial, especially for EGFR-mutant patients." (PMID 35069906, 2022). "Several clinical cases also report that the combination of gefitinib and letrozole (aromatase inhibitor) showed a synergic anti-tumor effect and the administration of estrogen reduced the effect of gefitinib in patient with lung adenocarcinoma concomitantly expressing ER and EGFR." (PMID 35664735, 2022). "Accumulate evidence demonstrated that CDKN2A is common in cerebrospinal fluid (CSF) samples of lung adenocarcinoma patients with central nervous system (CNS) metastases, and concurrent CDKN2A with EGFR-sensitive mutations indicated inferior median intracranial PFS (iPFS)." (PMID 35614407, 2022). "The most common TKI-sensitizing mutations in the EGFR are deletions in exon 19 that affect the LREA motif and substitutions in exon 21 (L858R), which together account for more than 90% of all EGFR mutations in lung adenocarcinoma (LA)." (PMID 35579943, 2022). "Epidermal growth factor receptor (EGFR) gene mutations are the most common driver oncogene mutations associated with non-small cell lung cancer (NSCLC), accounting for 55% of driver oncogene mutations in lung adenocarcinoma cases in East Asia." (PMID 34643820, 2022). "The SII and its dynamic change may have a prognostic value in patients with EGFR-mutant lung adenocarcinoma treated with BM radiotherapy." (PMID 35241046, 2022). "Finally, it should be noted that the study included three patients in whom EGFR detection was performed for treatment selection despite being diagnosed with stage II lung adenocarcinoma." (PMID 36497340, 2022). "The inclusion of patients with mutant EGFR-positive lung adenocarcinoma who became positive for T790M and were treated with osimertinib may also be a potential explanation for a better outcome in the ICI-untreated group." (PMID 35740634, 2022). "The third patient is a 63-year-old never-smoking female who was diagnosed with advanced-stage lung adenocarcinoma harboring an EGFR L747_A750delinsP mutation (exon 19 deletion)." (PMID 35566609, 2022). "EGFR mutations (14%) are more common in lung adenocarcinomas of patients who never smoked, and those who exhibit such mutations benefit from EGFR inhibitors." (PMID 35574381, 2022). "At present, the research progress of targeted therapy for epidermal growth factor receptor (EGFR) and anaplastic lymphoma kinase (ALK) gene mutations in lung adenocarcinoma is very rapid, which brings new hope for the treatment of advanced lung adenocarcinoma patients." (PMID 35340157, 2022). "However, a common pattern was that the MENL was highly focused its attention on the proximal bronchovascular bundle of the tumor with tumor inside for EGFR-mutant pGGN lung adenocarcinomas." (PMID 36119545, 2022). "Hence, this study aimed to present the prognostic value of SII and its dynamic changes during BM radiotherapy in EGFR-mutant lung adenocarcinoma patients with BM." (PMID 35241046, 2022).